ALB (albumin)
Diseases named in the same sentence as ALB in open-access papers (continued):
Sharing a sentence is not in itself a finding about the gene and the disease.
polyarthritis (1 paper, 2016). "This corresponds to the exact percentage of the serum albumin decrease caused by polyarthritis." (PMID 26835218, 2016). "However, the albumin thiol groups in polyarthritis were approximately half that of the controls and, thus, are more likely the consequence of both the diminished serum albumin levels combined with more oxidized levels of the sulfhydryl groups." (PMID 26835218, 2016). "However, four protein bands were strongly modified by polyarthritis when compared to the control condition: albumin was 34 % lower and alpha-1, alpha-2 and gamma were 500, 380 and 260 % higher, respectively." (PMID 26835218, 2016).
polyradiculoneuropathy (1 paper, 2025). Diseases characterized by injury or dysfunction involving multiple peripheral nerves and nerve roots. "Diagnosis is often supported by neuroconduction studies showing polyradiculoneuropathy and cerebrospinal fluid (CSF) analysis revealing albumin-cytological dissociation." (PMID 39896802, 2025).
Polyuria (1 paper, 2019). An increased rate of urine production. "At the end of the experimental protocol, diabetic mice showed polyuria (+195.5%), increase in Albumin-to-Creatine Ratio (ACR, +284.7%), and a significant drop in creatinine clearance (p < 0.05)." (PMID 31137660, 2019).
Primary hyperaldosteronism (1 paper, 2023). A form of hyperaldosteronism caused by a defect within the adrenal gland. "Studies on patients with non-primary hyperaldosteronism have shown that aldosterone levels are positively correlated with urinary albumin excretion rates." (PMID 37848834, 2023).
progressive bulbar palsy (1 paper, 2023). Progressive bulbar palsy involves the brain stem. "One patient with progressive bulbar palsy suffered repeat bleeding while receiving human albumin and required substitution of fibrinogen, cryo-precipitated factor concentrates and Factor XIII." (PMID 37109212, 2023).
promyelocytic leukemia (1 paper, 2019). "A ruthenium complex with thymine was reported to bind to DNA and human and bovine serum albumin and to induce caspase-mediated apoptosis in human promyelocytic leukemia HL-60 cells." (PMID 31338323, 2019).
Psoas abscess (1 paper, 2026). Abscess of the PSOAS MUSCLES resulting usually from disease of the lumbar vertebrae, with the pus descending into the muscle sheath. "Five predictor variables were screened by LASSO regression and plotted as a nomogram, including ALB, CRP normalization days, Bone graft materials, Psoas abscess, Jumping lesions." (PMID 42052375, 2026).
pulmonary infarct (1 paper, 2023). "Ischemia-modified albumin (IMA) was shown to be a sensitive marker in some acute ischemic conditions, such as cerebral, myocardial, or pulmonary infarct." (PMID 38255192, 2023).
radiodermatitis (1 paper, 2020). A cutaneous inflammatory reaction occurring as a result of exposure to biologically effective levels of ionizing radiation. "In multivariate logistic regression analysis, AJCC staging system, PNI and SIS were found to be independent risk factors for the radiodermatitis, whereas PNI, AST, ALB, and BUN were independent risk factors for radiation stomatitis." (PMID 32211311, 2020).
renal colic (1 paper, 2024). A severe intermittent and spasmodic pain in the lower back radiating to the groin, scrotum, and labia which is most commonly caused by a kidney stone (RENAL CALCULUS) passing through the URETER or by other urinary track blockage. "The top 14 characteristics are arranged as shown: N/L, HU value of effusion, hemoglobin, renal colic, globulin, WBC, albumin, PCT, IL-6 and blood neutrophils." (PMID 38896174, 2024).
retinal (1 paper, 2015). "This endothelial specific Tbdn knockdown model was previously shown to display retinal lesions characterized by significant thickening of all the retinal layers, abnormal vasculature with fibrovascular growth, and vascular hyperpermeability to Albumin." (PMID 26142315, 2015).
retinal arteriosclerosis (1 paper, 2024). "The associations of AMD with retinal arteriosclerosis, serum inorganic phosphate levels, and total albumin levels were established for the first time in this study." (PMID 39767587, 2024). "In addition to age, male sex, HTN, MCV, HBV carrier status, and serum UA levels, which are known to be associated with AMD, this study has, for the first time, established associations of AMD with retinal arteriosclerosis, serum inorganic phosphate levels, and total albumin levels." (PMID 39767587, 2024). "This study newly identified associations between retinal arteriosclerosis and both early/intermediate and advanced AMD, as well as associations between serum inorganic phosphate levels and total ALB levels with advanced AMD." (PMID 39767587, 2024).
retinal edema (1 paper, 2024). "Notably, leakage in macular telangiectasia does not cause retinal edema or thickening, suggesting a partial breakdown of the blood–retinal barrier and allowing for the passage of fluorescein but not albumin." (PMID 39001242, 2024).
rhabdomyosarcoma (1 paper, 1983). A rare aggressive malignant mesenchymal neoplasm arising from skeletal muscle. "Rat, mouse, pig and chicken alphafoetoproteins (AFP), rat serum albumin and egg albumin, or their fluoresceinated conjugates were added to cultures of several cloned cell lines isolated from a nickel-induced rat rhabdomyosarcoma." (PMID 6192837, 1983).
rickettsial diseases (1 paper, 2022). "There was a significant association between the groups of rickettsial diseases and elevated alanine aminotransferase/blood albumin levels." (PMID 35736967, 2022).
sarcomatoid carcinoma (1 paper, 2023). A malignant epithelial neoplasm characterized by the presence of spindle cells and anaplastic morphologic features. "The patient P001 was diagnosed as sarcomatoid carcinoma pathologically and was resistant to the first-line therapy of AS (Albumin-bound paclitaxel and S-1) before study entry." (PMID 37377605, 2023).
scrapie (1 paper, 2012). A fatal disease of the nervous system in sheep and goats, characterized by pruritus, debility, and locomotor incoordination. "Coinciding with this, there was a significant decrease in albumin concentration (p < 0.05) in the scrapie group (23.4 ± 0.8 mg/ml) compared to the control group (27.5 ± 0.9 mg/ml)." (PMID 22805457, 2012).
seminoma (1 paper, 2021). A radiosensitive malignant germ cell tumor found in the testis (especially undescended), and extragonadal sites (anterior mediastinum and pineal gland). "Serum from normal men (n:2), testicular germ cell cancer patients (1 seminoma, 1 non-seminoma), and pregnant women (n:2) was used for protein gel electrophoresis after albumin and globulin depletion." (PMID 33809538, 2021).
serous adenocarcinoma (1 paper, 2023). An adenocarcinoma that is characterized by the presence of papillary patterns and cellular budding. "Subgroup analyses demonstrated that LMR remained a prognostic factor in EOC patients with serous adenocarcinoma, good nutritional status (high albumin), and relatively high tumor burden (stage III/IV and high CA125)." (PMID 37035193, 2023).
serous ovarian cancer (1 paper, 2024). "Background/Objectives: The present study evaluates predictive implications of the pretherapeutic Fibrinogen–Albumin-Ratio Index (FARI) in high-grade serous ovarian cancer (HGSOC) patients undergoing primary cytoreductive surgery." (PMID 39409916, 2024).
signet ring cell carcinoma (1 paper, 2021). A usually aggressive, poorly differentiated invasive adenocarcinoma characterized by the presence of malignant glandular cells in which the nucleus is pressed to one side by the presence of intracytoplasmic mucus. "Between the NAC and S groups, several baseline characteristics had significant differences (P<0.05), including platelet, albumin, CA125, CA724, CEA, tumor differentiation, signet ring cell carcinoma component, Borrmann type and clinical N stage." (PMID 34497768, 2021). "There were 18 baseline parameters used for propensity score matching, including sex, age, BMI, hemoglobin, platelet, leukocyte, pre-albumin, total protein, albumin, CA125, CA199, CA724, CEA, AFP, tumor differentiation, signet ring cell carcinoma component, Borrmann type and clinical N stage." (PMID 34497768, 2021).
silicosis (1 paper, 2024). Silicosis is a respiratory disease caused by breathing in (inhaling) silica dust. "To improve the robustness of the biomarker set, we crossed the biomarkers screened by the three machine learning algorithms, LASSO, SVM, and RF, and finally developed a biomarker set that included eight potential diagnostic biomarkers for silicosis (A/G, ALB, CRP, DD, GLU, LDH, RBC, and WBC)." (PMID 39882130, 2024). "In this study, a lower A/G ratio was observed in the silicosis group, which may be due to both lower ALB levels in the silicosis group and an increase in inflammation-related globulin." (PMID 39882130, 2024). "Among selected biomarkers, WBC, RBC, ALB, GLU, and A/G showed lower levels in the silicosis group, while LDH, DD and CRP had the opposite trend." (PMID 39882130, 2024).
skin abscesses (1 paper, 2024). "Since serum albumin inhibits the activity of PPAP53, we analyzed whether topical application of PPAP53 could inhibit bacterial growth in skin abscesses." (PMID 39125595, 2024).
skin infection (1 paper, 2025). An inflammatory process affecting the skin, caused by bacteria, viruses, parasites, or fungi. "The results indicated that as albumin value exceed the normal range, the chances of skin infections caused by P. aeruginosa and K. pneumoniae increases." (PMID 40458522, 2025). "The results showed that albumin value increases beyond the normal range, the chances of skin infections caused by P. aeruginosa and K. pneumoniae may be increase." (PMID 40458522, 2025).
skull base meningioma (1 paper, 2023). A meningioma that arises from the skull base. "In a study of elderly patients with primarily low-grade, skull-base meningiomas, age, sex, KPS, tumor size, tumor location, and frailty (defined as a combination of body mass index and serum albumin levels) were evaluated as risk factors for postoperative deterioration over the course of one year." (PMID 37624530, 2023).
social phobia (1 paper, 2025). An anxiety disorder characterized by an intense, irrational fear of one or more social or performance situations in which the individual believes that he or she will be scrutinized by others. "The lower the fT3 levels, the longer the duration of evolution, the lower the albumin levels, and when AN occurred prior to the social phobia, the higher the level of social phobia symptoms." (PMID 40641314, 2025). "The lower the albumin level, the higher the level of social phobia (r = ‐0.21; p = 0.006)." (PMID 40641314, 2025).
squamous intraepithelial lesion (1 paper, 2022). "Theregression analysis revealed lower serum albumin levels in the low- andhigh-grade squamous intraepithelial lesion groups compared with the benigngroup." (PMID 36794669, 2022).
sudomotor dysfunction (1 paper, 2021). "Patients with sudomotor dysfunction had a higher level of blood urea nitrogen, a bigger proportion of suffering from DKD and a lower level of serum albumin (all P < 0.05)." (PMID 34702362, 2021).
T-cell acute lymphoblastic leukaemia (1 paper, 2025). "Composite indices such as the C-reactive protein/albumin ratio (CAR), the CRP × fibrinogen/albumin ratio (CFA), and the modified Glasgow Prognostic Score (mGPS) integrate these parameters, although their prognostic role in T-cell acute lymphoblastic leukaemia (T-ALL) remains underexplored." (PMID 41586228, 2025).
TAFRO syndrome (1 paper, 2018). "Notably—in addition to meeting the diagnostic criteria for TAFRO syndrome, significantly lower hemoglobin and lower albumin levels were shown in the TAFRO group than in the non-TAFRO group in this study." (PMID 29464312, 2018).
Telangiectasia (1 paper, 2022). Telangiectasias refer to small dilated blood vessels located near the surface of the skin or mucous membranes, measuring between 0.5 and 1 millimeter in diameter. "The consequences are imperfect vascular regeneration, leading to telangiectasia, increased vascular permeability, and hematuria, causing the release of albumin." (PMID 36101353, 2022). "Vascular lesions, telangiectasias and the presence of albumin can result in the activation of macrophages and mast cells, resulting in the release of large quantities of tryptase, which amplifies vascular lesions and fibrosis." (PMID 36101353, 2022). "This telangiectasia has been highlighted, with increased permeability of the blood vessels and immuno-histological observation of albumin around the small vessels." (PMID 36101353, 2022). "Secondly, telangiectasia and albumin promote chemokine production." (PMID 36101353, 2022).
Testicular atrophy (1 paper, 2006). Wasting (atrophy) of the testicle (the male gonad) manifested by a decrease in size and potentially by a loss of fertility. "At baseline, both groups with testicular atrophy showed similar serum levels of albumin, cholesterol, creatinine, alkaline phosphatase, glucose, total proteins and urea, which were all normal as compared with control rats." (PMID 16504030, 2006).
testicular cancer (1 paper, 2017). A primary or metastatic malignant neoplasm that affects the testis. "To further evaluate the potential association between serum albumin and risk of testicular cancer, we modelled a dose–response curve with restrictive cubic splines." (PMID 28900475, 2017).
theileriosis (1 paper, 2022). "Biochemical analysis revealed a significant decrease in total protein, albumin, and creatinine levels with a significant increase in urea and AST levels in infected sheep with theileriosis." (PMID 36590791, 2022).
Thrombophlebitis (1 paper, 2024). Inflammation of a vein associated with venous thrombosis (blood clot formation within the vein). "We also analyzed NLR, LDH and ALB that reflect inflammation and nutrition, and found HALP had a higher value for predicting the occurrence of thrombophlebitis." (PMID 39654256, 2024). "At the end of follow-up, ROC curves based on the incidence of thrombophlebitis were plotted to evaluate the efficacy of HALP, albumin (ALB), NLR, and lactate dehydrogenase (LDH)." (PMID 39654256, 2024). "This study analyzes the role of the hemoglobin, albumin, lymphocyte, and platelet score (HALP), a pre-catheterization blood parameter, in predicting the occurrence of thrombophlebitis." (PMID 39654256, 2024).
thymic atrophy (1 paper, 2024). "On day 3, thymic atrophy occurred, and increase in serum IFN-γ and decrease in serum ALB were recorded but the differences were not statistically significant, suggesting a systemic effect." (PMID 38525129, 2024).
thymic carcinoma (1 paper, 2023). Thymic carcinoma (TC) is a type of thymic epithelial neoplasm characterized by a high malignant potential. "Herein, we reported a 27-year-old male patient with thymic carcinoma who received the treatment of tislelizumab, paclitaxel albumin and carboplatin." (PMID 37869004, 2023).
tongue tumors (1 paper, 2025). "Notably, higher ORRs were observed in subgroups with primary tongue tumors, PD-L1 CPS ≥ 20, and low baseline levels of NLR, SII, and ALB." (PMID 41583496, 2025).
toxic epidermal necrolysis (1 paper, 2025). Toxic epidermal necrolysis (TEN) is an acute and severe skin disease with clinical and histological features characterized by the destruction and detachment of the skin epithelium and mucous membranes. "Notably, Tansil Tan and Nathasia applied albumin infusion therapy to pediatric and adult patients with toxic epidermal necrolysis (TEN), continuing it for 20 days." (PMID 40699702, 2025).
toxoplasmosis (1 paper, 2025). A parasitic disease contracted by the ingestion or fetal transmission of toxoplasma gondii. "The serum level of TP and albumin was significantly lower in the infected sheep with toxoplasmosis, with an increase in blood urea nitrogen (BUN), creatinine and AST levels." (PMID 39822153, 2025).
transmissible spongiform encephalopathy (1 paper, 2021). "Greater assurance that the HSA sourced is free of adventitious agents such as viruses and transmissible spongiform encephalopathy (TSE) could be achieved by the use of recombinant human albumin, which favourably preserved the stability of mesenchymal stromal cells with 10% DMSO." (PMID 34452278, 2021).
trisomy 21 (1 paper, 2012). A chromosomal disorder consisting of the presence of an extra chromosome 21. "Body-mass index, protein metabolism (BUN, total protein and albumin), and serum creatinine positively correlated with rates of lymphocyte respiration, but only in trisomy 21 children." (PMID 23249287, 2012).
typhoid fever (1 paper, 2025). A bacterial infectious disorder contracted by consumption of food or drink contaminated with Salmonella typhi. "Decline and normalization of hepatic transaminases was previously found to be indirectly proportional to increase in albumin levels in a cholestatic hepatitis-typhoid fever patient by Eranda and his colleagues, among a Sri Lanka population." (PMID 40911532, 2025).
uterine cancer (1 paper, 2024). Primary or metastatic malignant neoplasm involving the uterine corpus and/or the cervix. "Furthermore, negative consequences were reported in association with albumin levels <3.5 in cases of ovarian and uterine cancer." (PMID 39459466, 2024).
variant Creutzfeldt-Jakob disease (1 paper, 2009). A form of Creutzfeldt-Jakob disease that is most commonly contracted after consuming meat from an animal suffering from bovine spongiform encephalopathy. "This fact increases the biosafety of final products reducing risk of introducing prions of bovine spongiform encephalopathy (BSE) from bovine serum albumin and of infectious variant Creutzfeldt-Jakob Disease (vCJD) from human serum albumin." (PMID 19317892, 2009).
Vertigo (1 paper, 2022). An abnormal sensation of spinning while the body is actually stationary. "We found that ALB, fibrinogen, vertigo, duration of treatment, and hearing at 4,000 and 8,000 Hz were associated with SSNHL treatment outcomes." (PMID 36237617, 2022).
vestibular neuritis (1 paper, 2020). "Furthermore, the serum ALB redox status in patients with vestibular neuritis was significantly lower than in HCs, as was the incidence of MD." (PMID 33329359, 2020).
Weil's disease (1 paper, 2021). A jauncice caused by severe leptospirosis. "In previous work, we investigated the role of an acute increase in serum-free fatty acids levels observed in patients with Weil's disease, which can be represented mainly through OA/A and (OA + Linoleic/A) molar ratios and the serum albumin capacity to prevent in vitro NEUFA cytotoxic effects." (PMID 33732938, 2021).
Wilms' tumour (1 paper, 2002). "Increased excretion of albumin has been described in up to a third of patients surviving Wilms' tumour but was rare in our patients." (PMID 12402147, 2002).
α‐thalassemia (1 paper, 2022). "However, we did observe a significant reduction in urinary albumin: creatinine ratio (uACR) values in the HbSS cohort (p = .003), but not in the HbSC cohort (p = .82) with α‐thalassemia." (PMID 35802781, 2022).